PCIF1 (phosphorylated CTD interacting factor 1)
Diseases named in the same sentence as PCIF1 in open-access papers (continued):
Sharing a sentence is not in itself a finding about the gene and the disease.
tumor (continued). "This highlights the potential of dual targeting PCIF1 and PD1 as a novel therapeutic strategy for OSCC, leveraging their synergistic effects to maximize anti‐tumour efficacy." (PMID 40156159, 2025). "In our study, we identified overexpression of PCIF1 in RCC, providing evidence to support its essential role in driving tumor progression." (PMID 39422663, 2024). "In conclusion, our studies demonstrated that both PCIF1 and CTBP2 were independent predictors in patients with HNSCC, and patients with increased nuclear expression of PCIF1 and CTBP2 in tumor lesions tended to have an unfavorable prognosis." (PMID 37643007, 2023). "Researchers used PCIF1 KO and control CT26 cells to form Subcutaneous tumor in nude mice and use flow cytometry to analyze the immune cell type in tumor tissue." (PMID 37779183, 2023). "PCIF1 plays a role in immunotherapy resistance in CRC by modifying the m6Am landscape in mRNA and affecting the tumor–immune system interactions." (PMID 39524541, 2023). "After injection of the lipid nanoparticle-PCIF1 siRNAs formulation into the athymic nude mice with CRC, efficient silencing of PCIF1 in the tumor was observed and the tumor size was significantly reduced." (PMID 39524541, 2023). "The PCIF1 protein expression in UCEC and LUAD was much more higher in normal tissue than primary tumor (p < 0.01) on the contrary to that in clear cell RCC (p < 0.01)." (PMID 34888238, 2021). "Furthermore, in a preclinical mouse model, PCIF1 knockout enhanced the efficacy of anti‐PD1 immunotherapy, reducing tumour burden and improving histological outcomes." (PMID 40156159, 2025). "Additionally, PCIF1 regulates the TGF-β and interferon-gamma (IFN-γ) signaling pathways through m6Am-dependent mechanisms, thereby influencing the tumor microenvironment and response to immunotherapy." (PMID 41446042, 2025). "Our data suggest that PCIF1‐mediated m6Am modifications directly inhibit MTF2 translation, creating a feedback loop that disrupts chromatin‐mediated gene repression, thereby promoting tumour progression." (PMID 40156159, 2025). "Given that RNA modifications can influence drug resistance, metastasis and tumour microenvironment (TME) interactions, understanding how PCIF1‐mediated m6Am modifications contribute to OSCC malignancy may provide novel therapeutic targets for intervention." (PMID 40156159, 2025). "Instead, PCIF1 knockout appears to enhance anti‐PD1 efficacy by reducing tumour aggressiveness rather than altering the immune microenvironment, suggesting a novel mechanism for sensitizing tumours to immunotherapy." (PMID 40156159, 2025). "Specifically, while anti‐PD1 therapy alone modestly decreased Ki67 levels, the combination with PCIF1 knockout further suppressed cellular proliferation, implying that the absence of PCIF1 sensitizes tumours to immunotherapy." (PMID 40156159, 2025). "This indicates that the anti‐tumour effect of PCIF1 depletion operates through mechanisms independent of direct modulation of the immune microenvironment." (PMID 40156159, 2025). "To investigate whether targeting PCIF1 could enhance the efficacy of anti‐PD1 immunotherapy in OSCC, we conducted a comparative analysis of tumour progression in PCIF1‐knockout mice treated with either anti‐PD1 antibody or IgG control." (PMID 40156159, 2025). "PCIF1‐knockdown KYSE150 cells were injected subcutaneously into nude mice, resulting in a marked reduction in tumour volume and weight, confirming that PCIF1 promotes tumour growth." (PMID 40156159, 2025). "Consequently, Inhibition of the PCIF1/LPP3 axis significantly altered mitochondrial morphology and reduced RCC tumor progression." (PMID 39422663, 2024). "The results revealed that the double knockout of PCIF1 and CTBP2 did not exhibit substantial alterations in the tumor cell phenotype compared with the sole knockout of PCIF1." (PMID 37643007, 2023).
tumor (continued). "The tumor size after treatment with LNP-PCIF1 siRNA was significantly reduced, indicating that inhibiting PCIF1 could improve tumor treatment." (PMID 37779183, 2023). "PCIF1 knockdown makes CRC tumors more sensitive to anti-PD-1 therapy by increasing the population of natural killer cells and decreasing that of monocytic myeloid-derived suppressor cells in the tumor microenvironment." (PMID 39524541, 2023). "This suggests that PCIF1's tumour‐suppressive effects are independent of direct immune modulation." (PMID 40156159, 2025). "Notably, flow cytometry analysis indicated that PCIF1 primarily exerts its effects through tumour‐intrinsic mechanisms rather than direct modulation of the immune microenvironment, distinguishing its mode of action from PD1 blockade." (PMID 40156159, 2025). "However, the anti-tumor role of PCIF1 is not fully dependent on its methyltransferase activity." (PMID 39524541, 2023).
cancer (13 papers, 2021 to 2025). A tumor composed of atypical neoplastic, often pleomorphic cells that invade other tissues. "As one of the most prevalent RNA modifications in mRNAs, m6Am and the methyltransferase PCIF1 have been linked to cancer progression and therapeutic response across different cancer types." (PMID 37643007, 2023). "Previous study demonstrated the impact of PCIF1 on mRNA methylation and its implications for immune checkpoint therapy, providing foundational insights into its regulatory role in cancer." (PMID 40156159, 2025). "PCIF1 has been proven to play an important role in a variety of diseases, including cancers, viral infection, growth, development and endocrine diseases." (PMID 37779183, 2023). "A comprehensive understanding of the roles of PCIF1 in different types of cancers is essential for guiding therapeutic interventions." (PMID 39524541, 2023). "The oncogenic role of PCIF1 was also confirmed by Pan-cancer analysis and PCIF1 RNA was found to be upregulated in most tumors compared to normal tissues." (PMID 36768600, 2023). "The PCIF1-FOS-TGF-β pathway can be used not only as a target for cancer treatment, but also as a regulator of the ICB response." (PMID 37779183, 2023). "PCIF1 was found to be a strong inhibitor of bladder cancer growth in an in vivo functional RNA interference screen of hundreds of cancer-related genomic changes." (PMID 39524541, 2023). "Collectively, our work uncovers an oncogenic function of PCIF1, providing insights into the critical role of m6Am modification in cancer progression." (PMID 35597784, 2022). "Here, we provide evidences that m6Am modification and PCIF1 play a hitherto uncharacterized role in cancer progression." (PMID 35597784, 2022). "To explore the clinical relevance of the m6Am methyltransferase PCIF1 in cancers, we queried the Cancer Genome Atlas (TCGA) datasets." (PMID 35597784, 2022). "We attempt to primarily explore the oncogenic and immunogenic role of PCIF1 on the basis of the pan-cancer analysis." (PMID 34888238, 2021). "PCIF1 expression was higher in most cancers than normal tissues and was discrepant across pathological stages." (PMID 34888238, 2021). "A few progresses have been made in 2019 revealing the role of PCIF1 role as the only known m6Am methyltransferase, but still blank to cancer so far." (PMID 34888238, 2021). "Herein, we carried out a pan-cancer analysis of PCIF1, with a series of datasets (e.g., TIMER2.0, GEPIA2, cBioPortal)." (PMID 34888238, 2021). "PCIF1 expression was correlated with cancer prognosis and immune infiltration, suggesting it to be a potential target for cancer therapy." (PMID 34888238, 2021). "Furthermore, we demonstrated that PCIF1 enhances RCC cancer cell proliferation and migration both in vitro and in vivo, with its activity dependent on m6Am catalysis." (PMID 39422663, 2024). "Furthermore, the involvement of the PCIF1-mediated m6Am modification in cancer progression has been suggested in several human cancers." (PMID 39451207, 2024). "Abnormal levels of PCIF1 have been found to be involved in human cancers." (PMID 39524541, 2023). "PCIF1 and m6Am modification also have diverse functions in different cancers." (PMID 39524541, 2023). "PCIF1 could be a promising therapeutic target for both directly suppressing cancer development and modulating the response to immunotherapy, as physiological conditions, viability, and fertility are not affected by PCIF1 knockdown." (PMID 39524541, 2023). "The role of PCIF1 in facilitating cancer development suggests that targeting this modification could have beneficial effects on cancer treatment." (PMID 39524541, 2023). "Considering the differences of PCIF1 target genes may be involved in different cancer progression, it is possible that PCIF1 has individual function in different cancers." (PMID 35597784, 2022). "Our bioinformatics analysis reveals that PCIF1 expression is significantly changed in many cancers." (PMID 35597784, 2022).
cancer (continued). "It is interesting to investigate whether PCIF1 and m6Am modification have different functions in different cancers." (PMID 35597784, 2022). "So far, there were only two studies that demonstrated the role of PCIF1 in cancer." (PMID 34888238, 2021). "Uncovering oncogenic or immunogenic role of PCIF1 may be of great beneficial for cancer therapy, especially for immunotherapy or targeted therapy." (PMID 34888238, 2021). "It remained obscure whether the participation of PCIF1 in oncogenesis and cancer development is dependent on m6Am modification." (PMID 34888238, 2021). "Thus, the specific role of PCIF1 in cancer progression may vary depending on the cell or tissue type, which needs further investigation in other tumors." (PMID 39524541, 2023). "Therefore, we anticipate that controlling PCIF1 expression could suppress cancer progress and increase the efficacy of immunotherapy by controlling m6Am modification of target genes." (PMID 39524541, 2023). "Both the direct inhibition of PCIF1 expression through siRNA therapy and the inhibition of PCIF1 methyltransferase activity through structurally designed small molecule compounds suggest new possibilities to improve therapeutic strategies for patients with cancer." (PMID 39524541, 2023). "To elucidate the clinical significance of PCIF1 in OSCC, we first analyzed its expression across various cancer types using data from the TCGA database." (PMID 40156159, 2025). "Future research should focus on developing specific inhibitors of PCIF1, potentially in combination with epigenetic therapies aimed at restoring MTF2 function, to effectively manage OSCC and possibly other cancers influenced by similar regulatory mechanisms." (PMID 40156159, 2025). "Consequently, PCIF1 could be a promising and feasible therapeutic target for cancer." (PMID 39524541, 2023). "To assess the mRNA expression level of PCIF1 in HNSCC, we first analyzed The Cancer Genome Atlas (TCGA) Head-Neck Squamous Cell Carcinoma data sets." (PMID 37643007, 2023). "However, the biological role of m6Am modification and PCIF1 in human cancers is largely unknown." (PMID 35597784, 2022). "PCIF1/CAPAM knockout cells are viable, but sensitive to oxidative stress, a common adaptive advantage found in many types of cancer." (PMID 33376192, 2021). "Given that MTF2 restoration in our rescue experiments reversed the oncogenic effects of PCIF1 knockdown, targeting the PCIF1‐MTF2 axis could offer a promising therapeutic strategy, not only in OSCC but also in other cancers where this pathway is dysregulated." (PMID 40156159, 2025). "The role of PCIF1 in cancer was not extensively studied until its structure and function were further uncovered." (PMID 39524541, 2023). "Firstly, there were several cancer-related RNA modification regulators, such as m6Am regulators PCIF1 and METTL4, were not included in our analysis." (PMID 37007958, 2023). "In addition, G3BP2, WTAP, PCIF1, HNRNPA2B1, EIF3A, and IGF2BP2 were modulated in ≥three cancer types in uncertain manners." (PMID 35211628, 2022). "Overall, these findings imply that PCIF1's enzymatic activity may play a crucial role in the aggressive features of OSCC, highlighting its potential as a target for therapeutic strategies that aim to disrupt m6Am methylation in cancer cells." (PMID 40156159, 2025). "However, the pathological significance of PCIF1 in human cancers has not been investigated." (PMID 35597784, 2022).
infection (2 papers, 2021 to 2025). The state of being infected such as from the introduction of a foreign agent such as serum, vaccine, antigenic substance or organism. "During HIV infection, the mRNA of ETS1 was decreased at day 3 post-infection, which corresponds to a similar trend observed for PCIF1 degradation, indicating that ETS1 was regulated by PCIF1 during HIV replication." (PMID 34545078, 2021). "Comparative analysis of the formation of HIV late-RT cDNA at 10 h post-infection showed little effect of PCIF1 on HIV pre-integration." (PMID 34545078, 2021). "Infection with UL13null or US3null PRV yielded similar PCIF1 phosphorylation compared to WT infection, indicating that phosphorylation of PCIF1 during PRV infection is not caused by either of the two viral protein kinases." (PMID 39791911, 2025). "To address this question, we depleted PCIF1 in THP1 cells and differentiated them into macrophages followed by infection using HIVBaL, a CCR5-tropic strain." (PMID 34545078, 2021). "Integrated proviral HIV DNA analysis through Alu-viral LTR qPCR showed that PCIF1 did not affect HIV integration at 48 h after infection." (PMID 34545078, 2021). "By focusing on genes in the DNA-binding transcription factor category of molecular functions, we identified ETS1, which we found to be regulated by PCIF1 enzymatic activity and to play an important role in HIV replication and potentially in immune cell physiology during infection." (PMID 34545078, 2021). "Our results showed that despite robust infection, neither of the two strains reduced the mRNA levels of PCIF1." (PMID 34545078, 2021). "PCIF1 degradation was also observed in primary CD4+ T cells on days 2 and 3 post-infection." (PMID 34545078, 2021). "Since PCIF1 was not significantly changed at day 1 post-infection, suggesting that PCIF1 may not be the only factor affecting FOS and EGR1 expressions during HIV infection." (PMID 34545078, 2021).
PCIF1 also shares sentences with these, for which no sentence is quoted: glioblastoma (3 papers); Obesity (3); colon adenocarcinoma (2); acute respiratory distress syndrome (1); atherosclerosis (1); bone disorder (1); breast carcinoma (1); breast invasive carcinoma (1); cardiovascular disease (1); celiac disease (1); digestive system tumors (1); End-Stage Renal Failure (1); endocervical adenocarcinoma (1); endocrine diseases (1); hepatocellular carcinoma (1); inflammatory bowel disease (1); melanoma (1); peripheral T-cell lymphoma (1); prostate adenocarcinoma (1); psoriasis (1); rectum adenocarcinoma (1); rheumatoid arthritis (1); skin cutaneous melanoma (1); stomach adenocarcinoma (1); thymoma (1); type 2 diabetes (1).